CD99 (CD99 molecule (Xg blood group))
Diseases named in the same sentence as CD99 in open-access papers (continued):
Sharing a sentence is not in itself a finding about the gene and the disease.
Ewing sarcoma (continued). "For example, CD99 is highly expressed in several haematopoietic malignancies and in Ewing's sarcoma." (PMID 34374417, 2021). "Being an essential molecule for the malignancy of Ewing sarcoma, CD99 is another molecule being studied as a potential target for the treatment of this tumor." (PMID 32295254, 2020). "Whereas the silencing of endogenous CD99 revealed a tumor-promoting role in Ewing sarcoma, exogenous expression of CD99 uncovered a tumor-suppressing role in osteosarcoma." (PMID 33147457, 2020). "The silencing of CD99 was shown to inhibit the growth and migration of Ewing sarcoma cells or to induce neural differentiation in Ewing sarcoma cells and reduce their tumorigenicity and bone metastasis capability." (PMID 33147457, 2020). "Silencing of GDF6 or CD99 in Ewing sarcoma cells resulted in increased levels of active Src (active Src assessed by phosphorylation of tyrosine 419 in human Src)." (PMID 33147457, 2020). "The results show the expression of β3-AR on the surface of CD45− CD99+ PB cells, confirming the presence of β3-AR on tumour cells derived from Ewing sarcoma patients." (PMID 33066095, 2020). "For a patient with typical morphology, CD99 positive Ewing sarcoma, 88% of respondents felt FISH was a necessity to confirm the diagnoses." (PMID 33488267, 2020). "Immunohistochemistry (IHC) showed diffuse membranous positivity for CD99 in vaginal lesion, strongly suggesting a diagnosis of Ewing's sarcoma." (PMID 32629673, 2020). "Because the phenotype of CD99-silenced Ewing sarcoma cells resembles that of GDF6-silenced Ewing sarcoma cells, we tested the possibility that CD99 is the GDF6 prodomain receptor." (PMID 33147457, 2020). "We demonstrate that the GDF6 prodomain is a ligand for CD99, a transmembrane protein that has been widely used as a marker of Ewing sarcoma." (PMID 33147457, 2020). "Although mitogen-activated protein kinase (MAPK) was shown to be activated by CD99 silencing in Ewing sarcoma, GDF6 silencing still induced p21 when the MAPK pathway was suppressed by a MEK inhibitor, PD98059." (PMID 33147457, 2020). "A transmembrane protein, CD99, is highly expressed in Ewing sarcoma and has been commonly used as a marker for this cancer." (PMID 33147457, 2020). "Previous results in Ewing’s sarcoma cells, with a CD99 agonist antibody, demonstrated the ability of CD99 to control cell cytoskeleton remodeling and formed adherent junctions and focal adhesions, further corroborating the present findings." (PMID 30845661, 2019). "The accuracy of separating CSCs can be further improved by adding other selection windows, such as CD99 for Ewing sarcoma or MDM2 for liposarcoma." (PMID 31882696, 2019). "Even specific markers, such as CD99 for Ewing’s sarcoma, show background expression on normal hematopoietic cells." (PMID 31882696, 2019). "High CD99 expression plays an oncogenetic role in Ewing sarcoma, lymphoblastic lymphoma, myeloid chondrosarcoma, malignant glioma and so on." (PMID 30641946, 2019). "More recently, a ligand to CD99 extracellular region, clorafabine, inhibited malignant properties of Ewing sarcoma cells, opening new perspectives to target this molecule for cancer therapy." (PMID 30845661, 2019). "In Ewing sarcoma, triggering of CD99 by specific monoclonal antibodies activates hyperstimulation of micropinocytosis and leads to cancer cells killing through a caspase-independent, non-apoptotic pathway resembling methuosis." (PMID 29305692, 2018). "In fact, detecting high BCL11B and/or GLG1 expression in CD99-high tumors reached a specificity for Ewing sarcoma of at least 96%, and of 99% if both markers were highly expressed (defined as IRS > 9)." (PMID 29416716, 2018).
Ewing sarcoma (continued). "CD99 is frequently overexpressed in many types of tumors, particularly pediatric tumors including Ewing sarcoma and specific subtypes of leukemia." (PMID 29305692, 2018). "Particularly relevant and consistent is the sustained activation of the RAS/MAPK pathway in Ewing sarcoma cells deprived of CD99." (PMID 29534016, 2018). "Approximately 94% of cases stained positive for CD99 with a cytoplasmic and membranous staining pattern that was weaker and more diffuse than the typically homogeneous membranous staining seen in Ewing’s sarcoma." (PMID 29509716, 2018). "In fact, Ewing sarcoma cells deprived of CD99 but still presenting EWS-FLI1 showed dramatically inhibited growth, migration, and metastatic capabilities and were prone to differentiate toward the neural lineage." (PMID 29534016, 2018). "These analyses indicated that while CD99 is a very valuable marker for screening for Ewing sarcoma, it needs auxiliary markers to establish a robust diagnosis." (PMID 29416716, 2018). "While CD99 showed broad expression in many different tumor entities, ATP1A1, BCL11B, and GLG1 were only expressed at low levels in every tumor entity relative to Ewing sarcoma, indicating a higher specificity for this disease than CD99." (PMID 29416716, 2018). "Previously, another EWSR1-FLI1 target gene, NKX2-2, was proposed to serve in combination with CD99 as a useful immunohistochemical marker for Ewing sarcoma." (PMID 29416716, 2018). "The use of CD99 is limited by background expression on normal hematopoietic cells, and also by being somewhat specific for Ewing sarcoma." (PMID 29108279, 2017). "The author found a statistically significant relationship in CD99 expression in Ewing’s sarcoma, and therefore considers that this marker has a role in the diagnosis and prognosis of cancer." (PMID 28439237, 2017). "For instance, high CD99 expression is a hallmark of Ewing sarcoma (EWS), a malignant mesenchymal bone tumor, and CD99 expression is routinely assessed as a prognostic marker." (PMID 28903388, 2017). "CD99 is a cell surface molecule that has emerged as a novel target for Ewing sarcoma (EWS), an aggressive pediatric bone cancer." (PMID 27835596, 2016). "CD99 altered expression contributes to the Ewing’s tumor oncogenesis by modulating the growth and differentiation of tumor cells." (PMID 27144561, 2016). "A core needle biopsy showed bone that was infiltrated with poorly differentiated round malignant cells that were positive for CD99, which is consistent with a diagnosis of Ewing sarcoma." (PMID 29588868, 2016). "Biopsy revealed the diagnosis of Ewing sarcoma with characteristic small, round, and blue cell histology and typical strong and membranous immunohistochemical expression of CD99 protein." (PMID 27524931, 2016). "While evidence of direct binding of EWSR1-Fli1 to miR-30a-5p is lacking, over-expression of miR-30a-5p leads to reduction of cell proliferation and invasion as well as reduced CD99 expression in multiple Ewing sarcoma cell lines." (PMID 26204834, 2015). "Two cellular markers frequently employed by pathologists are CD-99, which is expressed in both Ewing's sarcoma and lymphoma, and CD-45, which is only expressed in lymphoblastic lymphoma." (PMID 25802527, 2015). "Histologically, these tumors appeared as sheets of small round blue cells and stained positive for common Ewing sarcoma cell surface markers, CD99, and NSE." (PMID 23443465, 2013). "Immunohistochemistry test done at another center using membranous staining with MIC2 (12E7) antigen (CD99) gave a final diagnosis of Ewing's sarcoma." (PMID 24198886, 2013). "Quite interestingly, the CD99 marker, which is commonly used for immunohistochemical testing for Ewing's sarcoma, is actually considered a normal leukocyte marker and is uniformly expressed on thymocytes." (PMID 20953407, 2011). "Another level-1 gene ranked within the top 10 for the SRBCT data set, CD99, is highly expressed in Ewing sarcomas (EWS) class." (PMID 21909426, 2011).
Ewing sarcoma (continued). "This addressed a previously raised concern against the theory of an MSC origin of Ewing's sarcoma regarding expression of CD99 in MSCs." (PMID 20953407, 2011). "Immunoreactivity of CD99 was detected in invasive malignant melanoma, in pancreatic endocrine tumors, Ewing's sarcoma and gastric cancer." (PMID 20175889, 2010). "CD99 are cell-surface glycoproteins highly expressed on thymocytes, Ewing's sarcoma, PNET cells, pancreatic islet cells, Leydig and Sertoli cells and moderately on haematopoietic cells." (PMID 18694498, 2008). "Our findings indicate that CD99-targeted nanoparticles may offer a promising therapeutic strategy for overcoming the limitations of conventional irinotecan therapy in Ewing sarcoma." (PMID 41542564, 2026). "To evaluate whether CD99-targeted irinotecan nanoparticles (NV103) could overcome resistance in relapsed Ewing sarcoma, we used CHLA-10, a cell line derived from a patient whose tumor progressed despite standard 5-agent VAC/IE chemotherapy." (PMID 41542564, 2026). "Immunoblotting demonstrated that all six Ewing’s tumor cell lines express CD99 at high levels." (PMID 41542564, 2026). "Ewing sarcoma typically shows strong membranous positivity for CD99 (MIC2) and may express FLI-1, aiding in its identification." (PMID 40084340, 2025). "Furthermore, IHC analysis of tumors confirmed the expression of the Ewing sarcoma marker CD99 and reduced levels of KDM6B and Ki-67." (PMID 41085408, 2025). "In contrast, Ewing sarcoma generally demonstrates strong membranous positivity for CD99 and may also show FLI-1, assisting in differentiation from other entities." (PMID 40084340, 2025). "Ewing sarcoma is a rare but aggressive type of cancer, primarily occurring in teenagers and young adults, characterized by having a small round cell morphology with positive diffuse membranous CD99 immunostaining of these small round blue cells." (PMID 40861426, 2025). "Resulting tumors were confirmed to be Ewing sarcoma with positive IHC staining for CD99, a membrane protein expressed uniformly in Ewing tumors, and nuclear staining of NK homeobox 2 (NKX2.2), a transcription factor upregulated by EWSR1::FLI1 fusion oncoprotein." (PMID 40858520, 2025). "Although NKX2.2 immunohistochemistry and EWSR1 rearrangement studies were not available in our setting to definitively exclude BCOR- or CIC-rearranged sarcomas, the characteristic morphology and diffuse membranous CD99 positivity strongly supported the diagnosis of Ewing sarcoma." (PMID 41278275, 2025). "Immunohistochemically, both tumors can express CD99, which is traditionally considered a marker for Ewing sarcoma; however, megakaryoblastic sarcoma may also show variable expression of this marker, making its interpretation more complex." (PMID 40565358, 2025). "CD99 came positive, favoring a differential of Ewing sarcoma or Ewing-like sarcomas." (PMID 40932977, 2025). "IHC established Ewing's sarcoma with CD99, FL1, and NKX2.2 positivity and a Ki-67 index of 40%." (PMID 40896068, 2025). "In addition, immunomagnetic separation techniques using markers such as CD99 for Ewing sarcoma have demonstrated high viability in isolating functional CTCs." (PMID 40679665, 2025). "This diagnostic approach is consistent with existing literature, which emphasizes that while CD99 is highly sensitive for Ewing sarcoma family tumors, it lacks specificity, making molecular confirmation-such as identification of the EWSR1-FLI1 translocation-critical." (PMID 41466962, 2025). "Notably, RAS/MAPK pathway activation continues in CD99-deprived Ewing sarcoma cells, with transient activation promoting proliferation and prolonged activation leading to neural differentiation." (PMID 40427525, 2025). "We next sought to determine whether anti-CD99 antibody treatment of mice harboring micro-metastatic Ewing sarcoma tumors could inhibit tumor growth." (PMID 38534214, 2024).
Ewing sarcoma (continued). "Moreover, Ewing sarcoma is notably characterized by its distinctive expression of CD99, which usually exhibits a diffuse and strong membranous pattern." (PMID 39439958, 2024). "With the knowledge that human macrophages express PILRα and confirmation that human PILRα binds human CD99, we next sought to evaluate the effects of blocking the macrophage PILRα:CD99 Ewing sarcoma binding axis on macrophage activity using TNF-α secretion as a proxy." (PMID 38534214, 2024). "CD99 is also intensely expressed by several cancer types, particularly Ewing’s sarcoma (ES)." (PMID 39595598, 2024). "ES constitutes a diagnostic challenge for neuropathologists because it does not express differentiation markers such as CD45, and may express CD99 which could be confused with CNS Ewing sarcoma." (PMID 38243303, 2024). "Ewing sarcoma is positive for vimentin and CD99 but lacks chondroid areas." (PMID 39503009, 2024). "Furthermore, the tumor cells exhibit a diffuse membranous expression of CD99, a characteristic marker in Ewing sarcoma." (PMID 38234938, 2023). "CD99 has been reportedly associated with several malignancies and has been found to actively contribute to the persistence of tumor malignancies, such as AML, lymphoma, ovarian carcinoma, and Ewing’s sarcoma." (PMID 37112766, 2023). "Yet, the Ewing sarcoma specificity increased when combined with CD99." (PMID 37444135, 2023). "In addition, neoplastic cells shared characteristics of conventional Ewing Sarcoma, with diffuse and strong membranous expression of CD99, nuclear expression of NKX2.2, with varying degree of nuclear positivity for FLI1." (PMID 37518334, 2023). "Interestingly, CD99 is an adhesion molecule, which is mainly upregulated in human Ewing sarcoma, and was a potential therapeutic target for hematological malignancies." (PMID 37021816, 2023). "IHC detection of FLI-1 is more specific for Ewing sarcoma than is CD99." (PMID 35372059, 2022). "In addition, a diffuse and strong membranous staining pattern for CD99 was universally considered as a highly sensitive and useful immunohistochemical biomarker for Ewing’s sarcoma." (PMID 36046048, 2022). "CD99 is a cell surface transmembrane protein highly expressed in all Ewing’s sarcomas." (PMID 35285802, 2022). "Since the tumor cells were expressing CD99, we have also discussed a Ewing sarcoma." (PMID 36414742, 2022). "The expression of CD99 can lead to the misdiagnosis of Ewing’s sarcoma." (PMID 36290813, 2022). "A few studies have reported the use of tumor-specific makers for CTC isolation and characterization in Ewing sarcoma patients, including CD99 expression and presence of chromosomal translocations, such as amplification of EWSR1-FLI1 transcript fusion gene, by using different methods." (PMID 36176757, 2022). "High CD99 expression has been shown in Ewing sarcoma, hence it was initially believed to be a specific marker for Ewing sarcoma and routinely used for the differential diagnosis of Ewing sarcoma from other types of small round-cell tumors." (PMID 35372059, 2022). "We demonstrated that clofarabine may have a novel function though inhibiting CD99, a transmembrane protein highly expressed on Ewing Sarcoma (ES) cells." (PMID 34133426, 2021). "CD99 is expressed on the surface of nearly all normal cell types including thymocytes, peripheral T cells, hematopoietic cells, and also several tumors including Ewing’s sarcoma." (PMID 33050232, 2020). "CD99 can be easily targeted by antibodies, and the availability of a human bivalent antigen-binding antibody directed against CD99 (dAbd C7) that can efficiently deliver a cell death message in Ewing sarcoma cells while sparing normal cells opens new therapeutic perspectives." (PMID 32295254, 2020). "CD99 is highly expressed in Ewing sarcoma and has been used as a marker for this cancer." (PMID 33147457, 2020).
Ewing sarcoma (continued). "Moreover, the presence of an intact IGF pathway as well as of CD99, a 32 kD integral membrane glycoprotein that is peculiarly and highly expressed in Ewing sarcoma cells, is also required for an EWS-FLI transformation." (PMID 32295254, 2020). "Since CD99 antigen is also expressed in synovial sarcoma and low-grade fibromyxoid sarcoma, patients were included in the study only after the clinical confirmation of Ewing sarcoma diagnosis, as described in method section." (PMID 33066095, 2020). "Ewing sarcoma cells have a high and specific expression of the CD99 antigen." (PMID 33066095, 2020). "CD99 silencing inhibits in vitro and in vivo growth of Ewing sarcoma." (PMID 33147457, 2020). "The preliminary results also show differences in the β3-AR expression between CTCs derived from metastatic and non-metastatic patients, and suggest a possible role of β3-AR as a new marker to be combined with CD99 for the prediction of recurrence or disease severity in Ewing sarcoma patients." (PMID 33066095, 2020). "CD99 is a marker of Ewing sarcoma and primitive neuroectodermal tumors." (PMID 31510956, 2019). "Additionally, and antibody against CD99 induced CD99 engagement and a consequent non apoptotic, caspase-independent programmed cell death of Ewing sarcoma cells, with micropinocytosis by a pathway that resembles methuosis." (PMID 30845661, 2019). "Thus, the following work-flow is proposed to establish a diagnosis of Ewing sarcoma: In the case of clinically and/or radiologically suspected Ewing sarcoma, a biopsy should first be stained for CD99." (PMID 29416716, 2018). "In addition, although the conventional immunohistochemical marker for Ewing Sarcoma (CD99) has high sensitivity it is also low specificity for the disease." (PMID 30120284, 2018). "Overall, CD99 is required for the Ewing sarcoma oncogenic phenotype." (PMID 29534016, 2018). "CD99 is thought to inhibit neural differentiation, and may contribute to oncogenesis in Ewing’s sarcoma." (PMID 29509716, 2018). "High expression of CD99 is a distinctive feature of Ewing sarcoma." (PMID 29534016, 2018). "In addition, CD99 positivity is observed in Ewing’s sarcoma and has also been reported as a potential positive marker for mesenchymal chondrosarcoma." (PMID 24932271, 2014). "A prognostic classifier for Ewing sarcoma with low cross-validation error rates (0.36) was comprised of multiple features, including the Ki67 proliferative marker and a sub-population of cells with low cytoplasmic/nuclear ratio of CD99." (PMID 25243408, 2014). "CD99 was reported to be expressed in most malignant pPNET and Ewing's sarcoma." (PMID 25587032, 2014). "Changes in cell morphology, CD99 up-regulation, neuroectodermal characteristics, repressed differentiation status and global gene expression profiles are all strikingly similar to profiles of Ewing sarcoma cell lines and primary tumors." (PMID 23443465, 2013). "Furthermore, the expression of CD99, a relatively specific marker for Ewing's sarcoma, was found to be present at a low level in MSCs and upregulated by EWS-FLI1." (PMID 20953407, 2011). "Although most Ewing sarcomas can be recognised morphologically and by immunohistochemistry for the surface glycoprotein CD99, Ewing sarcoma translocation detection is mandatory when the clinicopathological presentation is unusual or the histological diagnosis is doubtful." (PMID 21253474, 2010). "Finally, differential diagnosis of MCC from PNET is base on the negativity of the neoplastic Merkel cells for CD99, positive in Ewing's sarcoma/PNET." (PMID 18328106, 2008). "Therefore, small-blue-round-cell tumours of childhood and early adolescence that show high CD99 expression and the presence of a 22q12 aberration are often grouped under the term ‘Ewing tumours’ (ETs) or ‘Ewing family of tumours’ (EFTs)." (PMID 12087464, 2002).